MLANA (melan-A)
Description:
Involved in melanosome biogenesis by ensuring the stability of GPR143. Plays a vital role in the expression, stability, trafficking, and processing of melanocyte protein PMEL, which is critical to the formation of stage II melanosomes.
Synonyms: MART-1; MART1
Tractability: Antibody: its Gene Ontology location is reachable by antibodies, with high confidence; UniProt predicts a signal peptide or a membrane-spanning region.
Gene: Protein-coding gene on chromosome 9 (5,890,889 to 5,910,606, forward strand). Ensembl gene ENSG00000120215.
Subcellular location: Endoplasmic reticulum membrane; Golgi apparatus; Golgi apparatus, trans-Golgi network membrane; Melanosome
Pathways (Reactome):
Developmental Biology: Regulation of MITF-M-dependent genes involved in pigmentation
Gene Ontology:
Molecular function: protein binding
Cellular component: endoplasmic reticulum membrane; Golgi apparatus; melanosome; trans-Golgi network; melanosome membrane; plasma membrane
Genetic constraint (gnomAD): Loss-of-function variants: 16 observed, 10.35 expected, observed/expected ratio (o/e) 1.55, 90% interval 1.02 to 1.93. The upper end of that interval is the gene's LOEUF score, 1.93, which puts it in group 6 of 6, group 1 being the genes least tolerant of losing a copy. Missense variants: 115 observed, 109.13 expected, observed/expected ratio (o/e) 1.05, 90% interval 0.9 to 1.23. Synonymous variants: 44 observed, 42.49 expected, observed/expected ratio (o/e) 1.04, 90% interval 0.81 to 1.33.
Homologues: Orthologues: chimpanzee MLANA (100% identical), macaque MLANA (97% identical), dog MLANA (78% identical), pig MLANA (73% identical), rat Mlana (70% identical), guinea pig MLANA (68% identical), mouse Mlana (68% identical), rabbit MLANA (62% identical), tropical clawed frog mlana (40% identical).
Diseases named in the same sentence as MLANA in open-access papers:
MLANA is named in the same sentence as 139 diseases in open-access papers, as found by Europe PMC text mining. Sharing a sentence is not in itself a finding about the gene and the disease. The quoted sentences say what the papers report.
melanoma (588 papers, 1996 to 2026). A malignant, usually aggressive tumor composed of atypical, neoplastic melanocytes. "S-100 is a calcium-binding protein expressed by melanoma cells; Melan-A is a melanoma-associated antigen, and HMB-45 is a monoclonal antibody that targets the premelanosome protein gp100." (PMID 40422036, 2025). "The spatial phenotype of interactions between tryptase-positive mast cells (MCs) and atypical Melan-A+ cells in the melanoma microenvironment has significant diagnostic and prognostic potential, which can be used to individualize therapy." (PMID 41373472, 2025). "In one such trial, 24 patients with relapsed, high-risk melanoma were administered a peptide vaccine composed of melanosomal antigens such as Melan-A/MART-1, MAGE-1, gp100, and tyrosinase, along with granulocyte-macrophage colony-stimulating factor (GM-CSF)." (PMID 40746887, 2025). "The tumor's AFX-like morphology and partial loss of melanocytic markers (Melan-A negativity with retained SOX10 expression) represent a phenomenon of melanoma dedifferentiation." (PMID 40125165, 2025). "Immunostaining with Melanoma Antigen Recognized by T cells or Melan-A or microphthalmia-associated transcription factor was used for all cases, with Melanoma Antigen Recognized by T cells being most commonly used." (PMID 38756446, 2024). "Maintenance of the natural, and suboptimal, position 2 HLA A*02:01 anchor within the melanoma-associated Melan-A peptide EAAGIGILTV allows a cognate TCR to pull the peptide out of the MHC binding groove toward itself, thereby making a stronger interaction." (PMID 39286976, 2024). "Co-cultures with gp100- or Melan-A-specific cytotoxic T cells were used to assess immunogenicity of melanoma cells and associated T-cell responses." (PMID 37464364, 2023). "Direct intradermal administration of protamine-stabilized mRNA encoding for melanoma antigens (Melan-A, Tyrosinase, gp100, MAGE-A1, MAGE-A3, Survivin) to 21 metastatic melanoma patients was well-tolerated, inducing no adverse events of grade 3 or higher." (PMID 36992220, 2023). "Eleven clusters were annotated as tumor cells because they expressed high levels of melanoma-associated marker genes (MLANA, MITF, PRAME and SOX10)." (PMID 38065972, 2023). "Melan A, tyrosinase, and S100 are commonly used genes by pathologists to identify melanoma-associated proteins." (PMID 38260202, 2023). "We assessed the capacity of zDCs to induce Ag-specific CTL responses aimed at melanoma-associated peptides derived from proteins gp100, tyrosinase, and melan-A." (PMID 35269457, 2022). "This approach would have an advantage in that MITF expression is maintained, enabling continued expression of MITF target genes encoding immunogenic differentiation-associated melanoma antigens such as MLANA." (PMID 33789714, 2021). "The melanoma-associated antigen recognized by T-cells (MLANA) encoded by the MLANA gene is one of the major melanoma tumor antigens linked to immune recognition." (PMID 33789714, 2021). "Heterogeneity of canine melanomas is a complicating factor that will likely necessitate the use a panel of diagnostic markers, such as the immunodiagnostic cocktail of Melan-A, PNL2, TRP-1, and TRP-2." (PMID 34822659, 2021). "Collectively, these data indicate that TNFα was a potent suppressor of the MITF transcription factor and the associated melanoma antigen Melan A, particularly in the transitory and melanocytic melanomas, whereas NGFR and AXL induction were variable." (PMID 34073253, 2021). "The expression of MLANA is observed only in melanocytes, melanomas, and retinal pigment epithelium, suggesting its association with melanogenesis." (PMID 32694523, 2020). "Gene expression analysis of five melanoma-associated genes, including MLANA, TYR, MAGEA3, ABCB5 and PAX3, showed that at least one transcript was detected in 18 out of 43 samples analysed (42%)." (PMID 32037400, 2020).
melanoma (continued). "BRAF inhibition is associated with increased melanoma antigen expression, including Melan-A and TYRP2 (DCT)." (PMID 31354817, 2019). "Regression of metastatic melanoma with the concomitant occurrence of melanoma-associated leukoderma has been observed so far only in response to immunization with a Melan-A/MART-1 peptide." (PMID 31731645, 2019). "PBMCs obtained before and 1 month after M-ILP were cultured with presence of peptides from common viral antigens (HCMV/EBV/influenza virus) or melanoma-associated peptides (NY-ESO-1/Melan-A/gp100), supplemented with IL-2." (PMID 30560089, 2018). "The expansion of CD8+ T cells to the melanoma-associated peptides (NY-ESO-1/Melan-A/gp100) was more modest." (PMID 30560089, 2018). "A subsequent clinical trial used the Synchrovax vaccine encoding for four peptide epitopes of Melan-A and melanoma antigen recognized by T cells 1 to induce broad antigen-specific CD8+ T cell responses." (PMID 30445702, 2018). "Vaccination of melanoma patients with a bivalent DNA encoding Melan-A and tyrosinase as tumor-associated antigens elicited humoral and CTL responses in Stage IV patients." (PMID 30445702, 2018). "Immune selected melanoma cell clones, being resistant to lysis by Melan-A/MART-126-35 CTL were investigated for the underlying mechanism focusing on the role of the proteasomal antigen processing machinery." (PMID 27143649, 2016). "Rescue experiments reconstituting p97/VCP expression in melanoma cells resulted in enhanced Melan-A/MART-126-35 epitope recognition, underlining the in vivo functional relevance of our results." (PMID 27143649, 2016). "We previously reported that the presence of T cells responding in vitro to NY-ESO-1 and/or Melan A peptides was associated with longer survival of late-stage melanoma patients." (PMID 25849846, 2015). "We selected for the present in vitro study a 25-mer sequence of the Melan-A/MART-1 melanoma associated antigen bearing an anchor optimized analog of the immunodominant CD8+ epitope (epitope of Melan-A: Melan-A26–35 A27L on HLA-A2)." (PMID 24587108, 2014). "Twenty-four live CTCs were detected by GLV-1h254 in a 5 mL whole blood sample from the patient MM1 with malignant metastatic cutaneous melanoma and these CTCs were confirmed to express melanoma markers microphthalmia-associated transcription factor or Melan-A." (PMID 24019862, 2013). "Among the melanoma-associated Ags identified so far, Melan-A has received particular attention because of its immune dominance in HLA-A2+ patients." (PMID 19317896, 2009). "The discriminatory immunostaining pattern associated with the 'MCW Melanoma Cocktail' (mixture of Melan- A, MART- 1, and tyrosinase) facilitated the feasibility of intraoperative evaluation of imprint smears of SLNs for melanoma metastases." (PMID 15500702, 2004). "Similarly, the evaluation of premelanosome protein (PMEL) and melanoma antigen recognized by T cells 1 (Melan-A) expression, commonly used in melanoma diagnostics, carries the risk of ambiguity, as this marker can also be present on normal melanocytes 1,7." (PMID 40535809, 2025). "Given that Melan-A is one of the most common melanoma associated antigens, these results suggest that germline determined TRAV12-2 usage may play a role in anti-melanoma immunity." (PMID 40712021, 2025). "Moreover, in histological cross-sections melanoma nests were detectable by HE-staining and by immunohistochemical staining of the melanoma-associated markers MiTF, Melan-A, S100 and HMB-45." (PMID 36175453, 2022). "One critical effect of TNFα is the induction of melanoma dedifferentiation, characterized by the downregulation of the melanocytic antigen Melan A (MLANA gene) and the microphthalmia-associated transcription factor MITF, and the upregulation of NGFR and the AXL receptor tyrosine kinase." (PMID 34073253, 2021).
melanoma (continued). "Western blot analysis further showed that the hNVs contained specific protein markers of individual NVs, including CD61, an important marker for platelet adhesion and activation; CD14, an endotoxin receptor on macrophages; and Melan-A, a melanoma tumor-associated antigen." (PMID 32999291, 2020). "Importantly, we successfully identified two melanoma-specific markers, i.e., MITF (Microphthalmia-associated transcription factor) and MLANA (Melanoma antigen recognized by T-cells) in the exosome-exposed MSCs." (PMID 31681332, 2019). "In addition, Melan A and gp100, two specific and sensitive melanoma antigens associated with cell proliferation programs, were very elevated in Rn cell line." (PMID 29344558, 2017). "Next, we assessed whether the patient developed an immune response against melanoma-associated Melan-A (MART-1) antigen." (PMID 27504122, 2016). "However, some data indicate that loss of the expression of Melan-A in a melanoma metastasis favors the escape of this tumor from the immune response." (PMID 25853464, 2015). "The presence of Melan-A and melanoma-associated microRNAs argue that the isolated exosomes are indeed originating from the melanoma metastases, although some liver cell-derived exosomes may have been co-isolated with the melanoma-derived exosomes." (PMID 25510783, 2014). "MART-1, also known as Melan-A, is a commonly detected melanoma-associated Ag." (PMID 20016802, 2009). "However, the occuerence of pseudomelanocytic nests, known as aggregates of Melan-A positive cells at the dermoepidermal junction, may represent a diagnostic challenge in melanoma in situ associated with lichenoid inflammation." (PMID 36980327, 2023). "However, differentiating amelanotic spindloid melanomas from soft tissue sarcomas is challenging and often requires immunohistochemical labeling with a diagnostic cocktail that contains antibodies against Melan-A, PNL-2, TRP-1, and TRP-2 as the current gold standard." (PMID 35448673, 2022). "Initial histopathological evaluation suggested a spindle cell malignancy; however, immunohistochemical analysis demonstrated positivity for S-100, SOX10, and Melan-A, confirming malignant melanoma." (PMID 42220859, 2026). "Dissection of the right inguinal lymph nodes revealed melanoma metastasis in 10 of 14 lymph nodes, with Immunolohistochemistry showing diffusely positivity for Sox-10 and Melan-A." (PMID 41782886, 2026). "Histopathology revealed a mixed population consisting of squamous cell carcinoma and melanoma within the same lesion, also confirmed using immunohistochemical staining for high molecular-weight cytokeratins (HMWCKs) and Melan-A." (PMID 39846527, 2025). "There are several limitations to the use of Melan-A in the primary and differential diagnosis of melanoma." (PMID 40507250, 2025). "Immunohistochemical staining for markers, such as human melanoma black-45 and Melan-A, is crucial for confirmation." (PMID 39792728, 2025). "The role of NRAS mutations, especially in codon 61, is crucial in the development and progression of pCNS melanoma, alongside pathological markers like Melan A and HMB-45." (PMID 40417324, 2025). "Primary cutaneous melanomas express Melan-A in 73.3% to 83% of cases and is also maintained in melanoma metastases in 71% of cases." (PMID 40507250, 2025). "Among these, we detected co-upregulated melanoma marker gene MLANA and metabolic genes FASN, GPX3, and APOD, suggesting metabolic reprogramming as a key factor in invasiveness." (PMID 40866912, 2025). "Previous studies have demonstrated that activation of PI3K/AKT suppresses melanin accumulation in both murine melanocytes and human melanoma Melan-A cells." (PMID 41373883, 2025).
melanoma (continued). "The study included 46 paraffin-embedded melanoma samples, and the staining efficacy for markers such as Melan A, HMB-45, PRAME, and Ki-67 was assessed via both methods." (PMID 39930005, 2025). "The Melan-A stain result cannot help distinguish a benign nevi from melanoma, whereas the p16 stain supports a more benign condition as protein function is not silenced nor lost." (PMID 40123790, 2025). "GCP‐2 was overexpressed in Melan A‐negative fibroblasts (red, arrows) in the direct neighborhood of Melan A‐positive melanoma cells (yellow) of old patients (arrows), but not of young patients (arrows)." (PMID 41258756, 2025). "One study reported 59.6% of melanoma biopsies being measured by Melan-A stain as having a greater depth of tumour invasion than was measured by H&E, which led to 33% cases of melanoma in situ to be re-classified as invasive melanoma." (PMID 40507250, 2025). "By evaluating the IHC staining of commonly used markers in melanoma diagnosis and assessment—namely, Melan A, HMB-45, PRAME, and Ki-67 (The first two stain the cytoplasm, while the latter two stain the nucleus)." (PMID 39930005, 2025). "Immunohistochemistry demonstrated strong positivity for S-100, HMB-45, and Melan A, confirming the diagnosis of malignant melanoma." (PMID 40978962, 2025). "Additional examples of tumor self-antigens include lineage-restricted markers such as POU2AF1 in diffuse large B-cell lymphoma, oncoproteins from the CEACAM family in colon cancer, and known differentiation antigens like MLANA/MART1 in melanoma." (PMID 40672284, 2025). "Other significant correlations between melanoma immunohistochemical markers such as Melan-A, HMB45, S100 or PRAME and Breslow depth highlight their potential not only for diagnostic but also for prognostic purposes." (PMID 41155720, 2025). "A key diagnostic challenge arises from the complete or partial loss of expression of conventional melanocytic markers, including S100 protein, SRY-Box transcription factor 10 (SOX10), melanoma antigen A (Melan-A), and human melanoma black-45 (HMB-45)." (PMID 40125165, 2025). "Immunohistochemistry was negative for the melanocytic markers Human Melanoma Black 45 (HMB45) and melanoma antigen recognised by T cells 1/MART-1 (Melan-A)." (PMID 39402168, 2025). "Higher expression of MLANA and TYR have also been linked to phenotype switching in melanoma and is associated with a more differentiated phenotype." (PMID 40075679, 2025). "Modern histopathology routinely includes immunohistochemical stains, such as Sox-10 (Sry-related HMg box gene 10), Melan-A (Melanoma antigen recognised by T cells 1), and PRAME (Preferentially Expressed Antigen in Melanoma)." (PMID 41562710, 2025). "Immunohistochemical examination was performed on the patient, where the specimen tested positive for Melan-A, human melanoma black 45 (HMB45), S100, glial fibrillary acidic protein (GFAP), and epithelial membrane antigen (EMA)." (PMID 39996151, 2025). "The intensity of juxtacrine and paracrine colocalization of MCs with atypical melanoma cells was at its highest at stage II of the disease: approximately 40% of MCs in the intratumoral zone interacted with Melan-A+ cells." (PMID 41373472, 2025). "Histopathology confirmed orbital malignant melanoma, with tumor cells positive for S-100 (3+), Melan-A (3+), and HMB-45 (2+)." (PMID 41561965, 2025). "p < .05, including well‐known melanoma markers like MLANA, PMEL (HMB45) and multiple members of the S100 protein family." (PMID 41017066, 2025). "The second most common is an oncogene MLANA (protein melan-A), a transmembrane protein routinely expressed in malignant melanoma, which is used in 31 vaccines in total." (PMID 38204924, 2024). "The T cells were first incubated with EVs produced by melanoma cells before being cocultured with Melan-A+ target cells to evaluate their cytotoxic functions and phenotypic changes." (PMID 39492948, 2024).